CXCL12 (C-X-C motif chemokine ligand 12)
Diseases named in the same sentence as CXCL12 in open-access papers (continued):
Sharing a sentence is not in itself a finding about the gene and the disease.
tumor (continued). "SDF1 (also known as CXCL12) binds to receptors on PC cells and thereby plays a role in tumor-cell homing to the bone marrow." (PMID 40841830, 2025). "The CXCL12/CXCR4 interaction also promotes angiogenesis, the formation of new blood vessels, which is essential for tumor growth and providing nutrients to cancer cells." (PMID 40426863, 2025). "Abnormal tumor vessels further exacerbate hypoxia, which in turn increases the secretion of chemotactic cytokines - including CCL2, CCL22, CCL28, CXCL8, and CXCL12 - that recruit immunosuppressive MDSCs, M2-like TAMs, and Tregs into the tumor." (PMID 41019982, 2025). "On the other hand, the chemokine CXCL12 secreted by aHSCs can induce the quiescent state of NK cells through its homologous receptor CXCR4, thereby triggering the activation of tumor cells." (PMID 39966355, 2025). "Preclinical models show that CSF-1R inhibition reduces TAM infiltration, disrupts M2 programming, and downregulates the CXCL12/CXCR4 axis, an important pathway for tumor cell survival and chemoresistance." (PMID 41228234, 2025). "The CXCL12-CXCR4 signaling axis is another key pathway through which CAFs mediate tumor progression, and blocking the interaction between CXCL12 and its receptor CXCR4 can exert anti-tumor effects." (PMID 40890855, 2025). "CAFs, a key component of the TME, secrete a range of cytokines—including TGF‐β, ILs (IL‐2, IL‐6), chemokines (CXCL2, CXCL5, CXCL12), and FGF7—to support tumor cell proliferation." (PMID 41164803, 2025). "Chemokines such as C-X-C motif chemokine ligand 12 (CXCL12) regulate spatial immune cell recruitment and promote tumor-immune crosstalk within the brain TME." (PMID 40881677, 2025). "The attraction of MCs to a tumor requires the action of different chemokines produced by the tumor cells such as the stem cell factor (SCF), CXCL2, CCL2, CCL5, CCL11, CXCL12, CCL15, IL-3, and IL-33." (PMID 41465542, 2025). "For example, CAFs secreted IL-6, CXCL12, and MCP-1 promote the polarization of tumor-related macrophages toward the tumor-promoting phenotype M2, thereby impairing effector T cell responses and inducing immunosuppression." (PMID 40296919, 2025). "Compared to the oe‐NC+M2pep‐Cs NPs/Plerixafor group, the fluorescence intensity of CXCR4 in the tumor tissues of the oe‐CXCR4+M2pep‐Cs NPs/Plerixafor group was significantly increased; while, CXCL12 fluorescence intensity remained unchanged." (PMID 40536774, 2025). "CAFs remodel the ECM and enhance tumor cell invasiveness by secreting cytokines (e.g., TGF-β, IL-6) and chemokines (e.g., CCL2, CXCL12), promoting angiogenesis and inducing EMT." (PMID 41430036, 2025). "Another key axis is CXCL12/CXCR4, whose activation results in enhanced ERK and PI3K/AKT signaling in tumor cells, directly linking to increased vascular invasion and poor clinical prognosis." (PMID 41445734, 2025). "Macrophages emerged as key regulators, utilizing the CXCL12/CXCR4 axis to recruit CD8+ effector T cells and regulatory T cells (Tregs) into the tumor microenvironment (TME)." (PMID 41347146, 2025). "BC cells secrete TGF-β, increasing recruitment of CXCR4+ monocytes to perivascular fibroblasts producing CXCL12, forming a chemotactic gradient that promotes TAM migration toward the vasculature and facilitates tumor cell intravasation and dissemination." (PMID 40868199, 2025). "CXCL12, through interaction with CXCR4, regulates tumor cell survival, invasion, and immune suppression." (PMID 40426863, 2025). "The mobilization of dormant tumor cells from the PVN to the peripheral blood is mediated by C-X-C motif chemokine Receptor 4 (CXCR4) inhibition, suggesting that the axis CXCR4/CXCL12 (CXC motif chemokine 12) is crucial to anchor dormant tumor cells in the PVN." (PMID 39682261, 2024). "These tumor‐bearing mice were adoptively transferred with control or CXCR4+ B cells and saline or CXCL12." (PMID 39422063, 2024).
tumor (continued). "CXCL12 and CXCR4 are involved in developing tumor progression and distant metastases and can lead to resistance to chemotherapy in solid tumors." (PMID 38770000, 2024). "We assessed the levels of CXCL12 and CXCR4 in the sera of 49 OC patients, considering the clinicopathological characteristics and comparing them with classical tumor markers (SCC-Ag and CEA) and markers of inflammation—CRP." (PMID 38673838, 2024). "As verified by exocytotic chemokines, the expression of tumor-promoting chemokines, including CCL3, CCL5, CCL7, CCL11, CXCL1, and CXCL12, showed a downward trend after MWA." (PMID 38779358, 2024). "In a more detailed analysis, we found that among 28 subsets of tumor-infiltrating lymphocytes, 22 were correlated with CXCL2, 21 with CXCL12, 15 with CXCL14, and 19 with CXCL17." (PMID 38232115, 2024). "CXCL12 and its receptor; C-X-C motif chemokine receptor 4 (CXCR4) are involved in recruitment of tumor-promoting macrophages." (PMID 39003350, 2024). "The CAFs, recruited to the tumor site by TGF-beta and CXCR4/CXCL12 signaling, enhance cancer cell proliferation and polarize adaptive and innate immune cells toward a tumor-promoting phenotype (also conferring immunotherapy resistance)." (PMID 39950103, 2024). "Specifically, SOX12 transactivated CCL22, which resulted in the accumulation and enhanced activity of CCR4+Tregs within the tumor, whereas SOX18 up‐regulated CXCL12 expression, attracting CXCR4+TAMs and CXCR4+Tregs into the tumor." (PMID 39072947, 2024). "In order to recruit macrophages into the TME, tumor cells secrete various chemokines, including CSF-1, CCL2, CCL5, CX3CL1, and CXCL12." (PMID 38341519, 2024). "Among them, CAF-S1 enhances the migration of tumor cells and the initiation of EMT through signal cross talk involving both CXCL12 and TGF-β, while CAF-S4, due to its high contractility, is conducive to the invasion and movement of cancer cells." (PMID 38693304, 2024). "In a CXCL12-dependent manner, CAFs can effectively reduce the migration of CD8+ T cells towards the stromal region adjacent to the tumor, consequently limiting the infiltration of CD8+ T cells around tumor cells." (PMID 38542078, 2024). "We also observed colocalization of CXCL12+ fibroblasts with CXCR4+ CK17+ single tumor cells in the subcapsular sinus, the initial site of disseminated tumor cell arrival." (PMID 39236316, 2024). "Activation of lung epithelial TLR3 by RNAs in tumor-derived exosomes via NF-kB and MAPK pathways increased the production of chemokines such as CXCL1, CXCL2, CXCL5, and CXCL12, leading to the recruitment and accumulation of neutrophils for PMN formation." (PMID 38495881, 2024). "Spatial analysis of KS/PDX biopsies confirmed that CXCL12 was higher in tumor regions with fibroblast-clusters, while expression of CXCR4, the receptor of CXCL12 was higher in regions with KS signature clusters." (PMID 39386738, 2024). "Natural killer (NK) cells can migrate quickly to the tumor site to exert cytotoxic effects on tumors, and some chemokines, including CXCL8, CXCL10 or and CXCL12, can regulate the migration of NK cells." (PMID 38727264, 2024). "In melanoma, CD38-positive CAFs promote tumor cell migration and invasion, as well as endothelial cell tube formation, by secreting factors like VEGF-A, FGF-2, and CXCL-12 through paracrine signaling in vitro." (PMID 39534084, 2024). "A study showed that inhibition of the CXCL12/CXCR4 axis suppressed the accumulation of TAMs and sepsis-induced tumor progression in mice." (PMID 39403370, 2024).
tumor (continued). "Thereby, NOX-A12 disrupts CXCL12-dependent recruitment of circulating BMDC to the hypoxic tumor tissue, which prevents restoration of the tumor vasculature and hence restrains tumor cell growth in preclinical models." (PMID 38806504, 2024). "Moreover, iCAFs could specifically generate CXCL12 to interact with tumor-infiltrating myeloid cells through the activation of the CXCL12/CXCR4 axis to induce the M2 polarization of macrophages or restrain the antigen presentation of cDCs to suppress antitumor immunity." (PMID 39323622, 2024). "Additionally, systemic administration of CXCL12 may lead to off‐target effects, such as counteracting tumor‐secreted CXCL12, highlighting the need for optimized delivery methods, such as localized administration, to improve therapeutic specificity and minimize side effects." (PMID 39422063, 2024). "Selective inhibitors targeting CXCL12/CXCR4, such as plerixafor and BL-8040, have been investigated for their anti-tumor activities, showing variable effects in various cancers." (PMID 38898023, 2024). "This indicates that cell non-autonomous CXCL12 expression in the stroma may be a TME extracellular “cross-talk” signaling factor that promotes metastasis of cells from primary tumors by upregulating tumor-associated cell autonomous MDMX expression." (PMID 39766093, 2024). "For example, CAFs found in luminal non-specified and stroma-rich subtypes can secrete CXCL1, CXCL2, CXCL12, and CXCL14, contributing to tumor progression." (PMID 39409924, 2024). "VUF elicited immunoreactions by reducing CXCL12-mediated GAM induction, enhancing CD8+ T-cell activity, and promoting their infiltration into the tumor tissue." (PMID 38898023, 2024). "Furthermore, it was reported that SCF (Stem cell factor) and CXCL12 production by Lepr+ cells mediate persistence of hematopoietic stem cells in the bone marrow raising the possibility that these molecules are similarly involved in enhancing tumor cell homing in Lepr-β1 mice." (PMID 39413671, 2024). "In tumor regions, the expression levels of CCL2, CCL5, CCL20, CXCL9, CXCL10, CXCL11 and CXCL12 were generally higher in hot tumors than in the other two groups." (PMID 37847338, 2024). "We further extend this finding by elucidating the functional role of migratory tumor cells as a key modulator of different types of CAFs: IL6+ iCAF, CXCL12+ iCAF and myCAF." (PMID 38892065, 2024). "Tumor-derived CXCL16 interacts with MSC CXCR6 to modify MSCs into CAFs, which release significant amounts of CXCL12." (PMID 38745115, 2024). "The CXCL12/CXCR4/ACKR3 signaling axis activates the STAT3 pathway, playing a central role in tumor proliferation, metastasis, anti-apoptosis, maintenance of tumor stemness, and immune escape." (PMID 38920657, 2024). "Certain chemokines, such as CXCL12 and its receptor CXCR4, promote tumor cell migration and invasion, facilitating metastasis to distant organs." (PMID 39001498, 2024). "PI3 kinase, Ras, and AKT are all downstream effectors of the CXCL12/CXCR4 axis, and activation of them promotes tumor cell growth, spread, and migration." (PMID 39065562, 2024). "Further studies are required to fully elucidate how CXCL12 and other CAF-derived factors contribute to tumor progression and explore potential therapeutic strategies targeting these pathways." (PMID 39070795, 2024). "The spatial transcriptomic analysis reported herein revealed a compartmentalized expression pattern of CXCL12 in fibroblast-rich regions and CXCR4 in tumor regions dominated by KS signature cells, that is more pronounced in the PDX." (PMID 39386738, 2024). "CXCL12 plays a crucial role in tumour growth and metastasis by binding to its receptor, CXCR4, in the tumour cell membrane." (PMID 38766687, 2024). "These agents can disrupt the CXCL12/CXCR4 signaling pathway, thereby inhibiting tumor growth and metastasis." (PMID 39682247, 2024).
tumor (continued). "We found that the adoptive transfer of CXCR4+ B cells combined with CXCL12 effectively inhibited HCC progression and prolonged the survival time of tumor‐bearing mice." (PMID 39422063, 2024). "CCL2 and CXCL12 (also known as SDF-1) are among the most studied and most widely recognized cytokines recruiting monocytes into tumor tissue." (PMID 38455762, 2024). "We observed that MDA-MB-231 cells in culture, with added CXCL12, maintained some characteristics of the primary xenograft tumor and, as such, we asked if MDA-MB-231 circulating tumor cells (CTCs) derived from mice maintain CXCL12-responsive features." (PMID 39766093, 2024). "There is a growing body of evidence suggesting the presence of CXCL12 and its specific receptor CXCR4 in various tumor cells, indicating their potential involvement in different stages of tumor progression." (PMID 38673838, 2024). "In view of the role of CXCL12 in lymphocyte recruitment and GC formation in normal lymphoid tissues, we preliminarily explored the relationship between its expression in cHCC–CCA tumor tissue and the formation of TLSs." (PMID 38767772, 2024). "For instance, CAF-derived C-X-C motif chemokine ligand 12 (CXCL12) sequesters CD8+ T cells, which reduces CD8+ T-cell infiltration in the juxtatumoral compartment (identified as < 100 μm from the tumor)." (PMID 38715050, 2024). "The tumor-permissive and immunosuppressive characteristics of CXCR4/CXCL12 axis have fueled interest in therapeutically targeting this signal pathway." (PMID 38587644, 2024). "Collectively, the evidence suggests that CXCL12 plays a significant role in inducing EMT and stemness in tumor cells, with the Wnt/β-catenin pathway being a crucial mediator in this process." (PMID 39070795, 2024). "Activation of downstream CXCR4 signaling by CAF-derived CXCL12 promotes EMT and contributes to tumor stem cell activity." (PMID 39092186, 2024). "The presence of tumor-associated lymphatic vessels also promotes the exit of CD8+ T cells via the CXCL12 – CXCR4 chemotaxis, reducing the retention of tumor-specific CD8+ T cells." (PMID 39211044, 2024). "CXCL12-induced resistance primarily occurs via activation of the CXCL12/CXCR4 axis, initiating downstream signaling cascades in tumor cells, including Akt, ERK, and Wnt/β-catenin pathways." (PMID 38818409, 2024). "The authors demonstrated that the ligand, CXCL12, stimulated the CXCR4-expressing TNBC cell line, MDAMB-231, and led to an increase in the chemotaxis and chemoinvasion of tumor cells toward its ligand." (PMID 39001456, 2024). "CXCR4 is expressed on the macrophage surface, and it is involved in their tumor recruitment as well as in CAF interactions, desmoplasia, and T cell infiltration through the binding of its ligand, CXCL12." (PMID 38730724, 2024). "The control of the flow rate in 3D dynamic model is particularly relevant, especially considering the application of CXCL12, as a mean to attract GBM cells that have invaded the surrounding peri-tumoral tissue post-tumor resection." (PMID 39715221, 2024). "CEBPB is an important cytokines response transcription factor, the chemokines CXCL12 induced recruitment of Tregs via CEBPB/NF-κB signaling to promote drug resistance, thus the inhibition of CEBPB benefited the tumor treatment." (PMID 38227591, 2024). "Another example is CXCL12, which, in addition to the PI3K/Akt and JAK/STAT pathways, promotes tumor cell proliferation by activating the Wnt/β-linker protein signaling pathway, which has been associated with tumor invasiveness and treatment resistance." (PMID 38791448, 2024). "For example, the blocking of CCL2 can inhibit metastasis of tumors and interrupt the CXCR4/CXCL12 chemokine axis, which can be used to sensitize drug-resistant tumor cells to chemotherapy or radiotherapy and may inhibit angiogenesis and proliferation of tumor cell." (PMID 38578317, 2024).
tumor (continued). "CXCL12 RNA levels were lower in HCC tissues than in normal liver and adjacent tumor tissues, and low expression of CXCL12 indicated poor clinical outcomes in patients with HCC." (PMID 39422063, 2024). "In vivo therapeutic efficacy was longitudinally monitored using serial 18F-FDG, [18F]AlF-NOTA-FAPI-04, and [68Ga]Ga-DOTA-Pentixafor PET/CT scans and validated using tumor sections through immunohistochemical staining of Ki-67, α-SMA, CXCR4, and CXCL12." (PMID 38587644, 2024). "Crucially, MDSCs are recruited to tumor sites via various chemokine axes, such as CCL8/CCR2, CCL5/CCR5, CXCL5/CXCR2, and CXCL12/CXCR4." (PMID 39769501, 2024). "The reciprocal modulation between the CXCL12/CXCR4/ACKR3 axis and the STAT3 signaling pathway plays a crucial role in the progression of various diseases and neoplasms." (PMID 38920657, 2024). "At the same time, extracellular tumor-promoting chemokines, such as CCL3, CCL5, CCL7, CCL11, CXCL1, and CXCL12, were also downregulated." (PMID 38779358, 2024). "A higher concentration of CXCL12 in lymph nodes, lung, liver, and bone/bone marrow (BM) is thought to direct the metastasis of CXCR4-expressing tumor cells." (PMID 39001265, 2024). "In contrast, the expression of genes such as CXCL12 (C-X-C motif chemokine ligand 2) and DST (dystonin) exhibited an increase in TR in most normal tissues compared to tumor samples." (PMID 39349823, 2024). "When methylation levels were analyzed against clinical outcomes, we found 4 CpG sites around CXCL2, 16 CpG sites around CXCL12, and 3 CpG sites around CXCL14/17 where altered methylation appeared to affect tumor behavior and patients’ outcomes." (PMID 38232115, 2024). "CXCL16 is indicated to play a critical role in MSC-boosted tumor metastasis by facilitating MSC recruitment and conversion to CAFs that secrete CXCL12 to regulate EMT in tumor cells." (PMID 38951845, 2024). "The results of this study suggest the potential value of tumor CXCL12 expression as a marker to predict prognosis and to indicate adjuvant chemotherapy in NSCLC patients that underwent surgical tumor resection." (PMID 37227446, 2023). "This is because tumor regions are enriched with CAFs expressing fibroblast activating protein (FAP), which inhibits T lymphocyte aggregation by producing CXCL12." (PMID 37217855, 2023). "It is well established that EMT process is associated with tumour angiogenesis, and SLUG expressed in tumour cells promotes the angiogenesis through VEGFA and CXCL12 production." (PMID 37867401, 2023). "By releasing chemoattractant factors, including monocyte chemoattractant protein-1 (CCL2/MCP-1) or even stromal cell-derived factor 1 (CXCL12/SDF-1), tumor cells actively recruit circulating monocytes and facilitate their migration to the tumor area." (PMID 36986856, 2023). "Fibroblasts colonized by H. pylori, CAFs, release proinflammatory factors (COX-2, CXCL1, CXCL9, CXCL10, CXCL12, IL-6, and FSP1) and are involved in inducing tumor growth and neoplastic cell invasion." (PMID 37609398, 2023). "In multiple myeloma, CXCL12/CXCR4 signaling has been shown to promote proliferation, migration, invasion, metastasis, chemoresistance, and tumor-induced osteoclastogenesis." (PMID 37025604, 2023). "In a pro-tumor model induced by Pit-1, Pit-1 exerted a pro-angiogenic effect through increasing the expression of CXCR4 and CXCL12." (PMID 37497001, 2023). "The M2 macrophages migrate towards nearby blood vessels, up spatial gradients in CXCL12, and the CSF-1/EGF paracrine loop enables tumour cells to trail behind them." (PMID 36972297, 2023). "Mast cells are recruited to the TME by cytokines produced by tumor cells such as vascular endothelial growth factors (VEGFs), angiogenic hormone (ANGPT1), CCL2, and CXCL12 chemokines." (PMID 37161430, 2023). "Other CAF-derived molecules, such as the chemokine CXCL12 or the extracellular protease MMP2, have also been shown to promote the proliferation and invasion of tumor cells in diverse cancers." (PMID 37566084, 2023).